LBP (lipopolysaccharide binding protein)
Diseases named in the same sentence as LBP in open-access papers (continued):
Sharing a sentence is not in itself a finding about the gene and the disease.
Sepsis (continued). "Levels of HMGB1, PCT and LBP were higher in infected patients compared with those in healthy controls, and levels were higher in severe sepsis patients compared with those in sepsis patients." (PMID 17625012, 2007). "Using a cut-off level of 20 μg/ml, LBP had a sensitivity of 81.0% and a specificity of 68.4% in diagnosing sepsis/severe sepsis." (PMID 16569262, 2006). "We studied the ability of procalcitonin, lipopolysaccharide-binding protein, IL-6 and C-reactive protein to identify patients with infection and sepsis." (PMID 16569262, 2006). "IL-6, lipopolysaccharide-binding protein and C-reactive protein performed best in distinguishing between systemic inflammatory response syndrome and sepsis, with an area under the curve larger than 0.84 (P < 0.01)." (PMID 16569262, 2006). "The associations of plasma LBP levels with the need for dialysis (12 females and 41 males), mechanical ventilation (27 females and 67 males), or vasopressor treatment (24 females and 76 males) were calculated for the SIRS/sepsis patients." (PMID 39997462, 2025). "However, in the SIRS/sepsis patient cohort, the 34 patients with liver cirrhosis had reduced plasma LBP levels (p = 0.001)." (PMID 39997462, 2025). "However, high levels of LBP, such as those found in patients with severe sepsis or septic shock, have been shown to inhibit the LPS response of human macrophages, suggesting a protective role for elevated serum LBP in sepsis." (PMID 39997462, 2025). "Moreover, patients with SIRS, sepsis, and septic shock had comparable plasma LBP levels in both sexes." (PMID 39997462, 2025). "Strongly increased serum LBP levels have been described in sepsis and septic shock." (PMID 39997462, 2025). "However, higher LBP levels have been reported in other diseases such as Crohn's disease, sepsis, and atherosclerosis." (PMID 35224112, 2022). "In BAT, the rise of LBP mRNA was the most significant effect of CLP-induced sepsis." (PMID 34322037, 2021). "However, an enrichment of lipopolysaccharide synthesis was observed in stroke cases as compared to healthy controls, and the presence of LBP can increase the rate of sepsis in stroke mice." (PMID 33439913, 2021). "Impact of SNPs in LBP gene on infectious diseases, sepsis and septic complications." (PMID 34295331, 2021). "The authors defined wild-type homozygotes as A, heterozygotes and mutant homozygotes as B. Among analyses of BPI, TLR and LBP, LBP A + BPI A + TLR A was associated with a high risk of sepsis (p=0.005), LBP B + BPI A + TLR A was a high-risk combination for sepsis with severe condition (p=0.034)." (PMID 34295331, 2021). "Thus, the clinical setting described here differs from that of sepsis and septic patients, in which massive, acute LPS exposure promotes very high LBP concentrations that inhibit the LPS response by human monocytes and is therefore thought to be protective." (PMID 33451043, 2021). "Conversely, they highlighted that LBP measurement in pericardial fluid cannot be considered as an alternative option to blood, because blood and pericardial fluid LBP levels were incomparable in both sepsis and non-sepsis cases." (PMID 33092081, 2020). "Lipopolysaccharide-binding protein (LPB) is released into blood as a type I acute-phase reactant after bacteremia or endotoxemia; an increase in postmortem serum LBP levels has been observed in sepsis groups, with a marked decrease correlated with interval after death." (PMID 31661804, 2019). "Haptoglobin, LBP, and the serpins in particular responded with a clear linear increase in plasma levels over the first 24 h after SE infection, suggesting their high relevance as early markers of sepsis and bacterial infection." (PMID 31803186, 2019).
Sepsis (continued). "Compared with classical blood biomarkers of systemic inflammation (e.g., CRP), the proteins detected in this study, including haptoglobin, vWF, MBL1, MRC1, sCD14, and LBP, showed a very early response to infection, indicating their potential in serving as new early markers of infection or sepsis." (PMID 31803186, 2019). "We also showed that CPFA treatment reduced the PMT through a mechanism mediated by LBP removal, which might represent a potential strategy to prevent early fibrosis in patients with sepsis-induced AKI." (PMID 31357597, 2019). "We also show that CPFA treatment reduces PMT through a mechanism mediated by LBP removal, which might represent a potential strategy to prevent the occurrence of early fibrosis in patients with sepsis-induced AKI." (PMID 31357597, 2019). "Since the response of an organism to LPS sepsis involves production of LBP, an acute phase protein, by the liver, we tested in whether hyperbilirubinemia might affect production of this mediator." (PMID 31075981, 2019). "Furthermore, retrospective trial evidence suggested that this LBP SNP was correlated with increased mortality rate during sepsis and pneumonia." (PMID 30479651, 2018). "As high levels of LBP can actually dampen the inflammatory response to LPS during sepsis, and injection of LPB rescues septic mice, the inability of aged mice to mount an effective LBP response may be a primary mechanism behind their susceptibility to sepsis." (PMID 27115295, 2016). "Commercial methods for the automated measurement of the soluble CD14 subtype presepsin (sCD14-ST) and lipopolysaccharide binding protein (LBP), the two old biomarkers, have been proposed over the past years to manage critically ill newborns with acute inflammation and sepsis." (PMID 26063982, 2015). "Their synthesis in sepsis is due to the interaction between a fraction of a lipopolysaccharide (LPS) and a protein normally present in the human body, respectively, lipopolysaccharide binding protein (LBP), with the CD14 receptor on the surface of macrophages." (PMID 26221578, 2015). "It has been shown in different models that upregulation of LBP prior to an LPS challenge potentiates the inflammatory response which may largely contribute to LPS toxicity in sepsis." (PMID 26798659, 2015). "STATs may increase LPS signaling molecules, including lipopolysaccharide binding protein and MD-2, indicating that STATs may expand the inflammatory response in the development of sepsis." (PMID 25371731, 2014). "Analyses of the specific triplet LBP, TLR and IL-6 showed LBP A + TLR B + IL-6 A and LBP B + TLR A + IL-6 A combinations (P = 0.006; P = 0.012, respectively) to be at high risk for sepsis development, but occurrence of the proposed variants was low (4.2 and 4.8% of patients)." (PMID 24383711, 2014). "Moreover, MT was indirectly confirmed by increased levels of LBP and sCD14 as observed in sepsis patients." (PMID 23717702, 2013). "Increased LBP concentrations have been found in patients with severe sepsis caused by Gram-negative or Gram-positive bacterial infections or fungal infections." (PMID 22348735, 2012). "However, as LBP plasma levels have been shown to correlate with sepsis severity, differences in LBP plasma concentrations between S and NS are to be expected in inhomogeneous populations with different levels of severity." (PMID 21901123, 2011). "Therefore, a moderate re-increase in LBP or CRP plasma concentration in the second week of sepsis is no reliable indicator of a recurrent infection in this setting of postoperative sepsis." (PMID 21901123, 2011). "Importantly, the level of LBP has been used as an important biomarker in sepsis and septic shock patients, where its levels increase up to 10-fold." (PMID 22028888, 2011).
Sepsis (continued). "In this study, using a large, multicenter cohort of patients meeting the international criteria for severe sepsis, we hypothesized that the pattern of LBP serum levels during the first week of severe sepsis development is a marker of severity and prognosis." (PMID 19718443, 2009). "We also anticipate that pharmacologic modulation of LBP activation may represent a novel target for future therapeutic trials in the setting of severe sepsis." (PMID 19718443, 2009). "Plasma LBP and LPS levels both have prognostic significance in patients with sepsis." (PMID 18575590, 2008). "A few studies have investigated LBP levels in infection and sepsis." (PMID 16569262, 2006). "IL-6, LBP and CRP appear to be superior as diagnostic sepsis markers compared with PCT." (PMID 16569262, 2006). "However, gender-specific studies of circulating LBP levels in sepsis patients are scarce." (PMID 39997462, 2025). "LBP blockade could be considered a novel strategy in modulation of inflammatory response in sepsis." (PMID 30525057, 2018). "We previously found that the rs2232618 (Phe436Leu) polymorphism in LBP had a significant association with the incidence of sepsis and MOD score in two non-dependent cohorts of major traumatic patients admitted from Chongqing (Southwest of China) and Zhejiang (Southeast of China)." (PMID 30479651, 2018). "Therefore, we hypothesized that the dynamic balance between LBP-mediated LPS-sensitization and bacterial clearance was decisive for the therapeutic success of G-CSF-induced modulation of innate immunity in sepsis." (PMID 30525057, 2018). "This study was designed to explore whether the dynamic balance between LBP-induced bacterial clearance and LBP-mediated LPS-sensitization was decisive for the therapeutic success of G-CSF-induced modulation of innate immunity in sepsis." (PMID 30525057, 2018). "We performed a prospective, multicenter, observational study to investigate the time-course of lipopolysaccharide binding protein (LBP) serum levels in patients with severe sepsis and examined whether serial serum levels of LBP could be used as a marker of outcome." (PMID 19718443, 2009). "Serial LBP serum measurements may offer a clinically useful biomarker for identification of patients with severe sepsis having the worst outcomes and the highest probability of developing sepsis-induced ARDS." (PMID 19718443, 2009). "Our findings indicate that serial LBP serum measurements may offer a clinically useful biomarker for identification of patients, with severe sepsis, having the worst outcomes and the highest probability of developing sepsis-induced ARDS." (PMID 19718443, 2009). "Serum levels of LBP were approximately six times higher in patients with systemic inflammatory response syndrome (SIRS) and sepsis compared to healthy controls, and were further elevated in patients with septic shock." (PMID 39997462, 2025). "When compared by gender, LBP levels were higher in both male and female SIRS/sepsis patients than in the respective controls (p < 0.001 for both)." (PMID 39997462, 2025). "According to various studies, serum LBP levels were significantly higher at admission in patients with SIRS, sepsis, and septic shock compared with a group of healthy subjects and in non-survivors compared with survivors." (PMID 40075763, 2025). "Several protein biomarkers have already been proposed as prognostic markers of sepsis, such as CRP, lipopolysaccharide binding protein, PCT, or cytokines such as tumor necrosis factor-α and interleukin-6." (PMID 39335614, 2024). "According to the previous study, the dysregulated inflammatory response initiated by the interaction between lipopolysaccharide-binding protein (LBP) and LPS is closely related to the development of sepsis." (PMID 35005033, 2021). "S100A9; LBP; soluble ST2 (sST2), which serves as a decoy receptor for IL-33; and RAGE (also known as AGER) have been used as prognostic biomarkers in sepsis." (PMID 33232303, 2021).
Sepsis (continued). "Candidate gene studies for traumatic patients identified several SNPs in lipopolysaccharide-binding protein (LBP), toll-like receptor 1(TLR1), and tumor necrosis factor-alpha (TNF-α) which were related to the development of sepsis." (PMID 30479651, 2018). "The role of G-CSF pretreatment and subsequent LBP upregulation was investigated in a SIRS model and a sepsis model." (PMID 26798659, 2015). "Compared with controls, LPS-challenged volunteers and patients with sepsis both exhibited increased concentrations of polymorphonuclear leukocyte surface BPI and plasma LBP." (PMID 26347737, 2015). "To determine if the translocation of the pathogen had an effect on systemic inflammation, we examined sera for the presence of LPS binding protein (LBP), a clinical marker of sepsis." (PMID 23405155, 2013). "In our opinion this does not represent a major limitation, since biomarkers, including LBP and CRP, were found to be the highest on the third day after the onset of sepsis." (PMID 24349403, 2013). "In conclusion, our study demonstrates that LBP and CRP plasma concentrations are well correlated with each other and change concordantly in the course of sepsis." (PMID 21901123, 2011). "During the first week of sepsis, both CRP and LBP showed the highest plasma levels at d2 or d3 after onset of sepsis with median values above 100 mg/L and 50 mg/L, respectively, in both groups (S and NS)." (PMID 21901123, 2011). "Similar findings were reported for LBP (AUC = .53) and CRP (AUC = .56) plasma concentrations on ICU admission in a heterogeneous population of postoperative patients with SIRS, sepsis or septic shock." (PMID 21901123, 2011). "Due to a broad overlap between S and NS both in LBP and CRP plasma concentrations during the first 5 days of sepsis, their predictive accuracy for mortality (at day 28) as assessed by ROC-analysis was very poor (AUC<.55)." (PMID 21901123, 2011). "LBP and CRP plasma concentrations, assessed in intervals of 24 hours and more, rather show a very similar kinetics in the course of sepsis." (PMID 21901123, 2011). "In acute and chronic inflammation, infection, sepsis and MS, there is an impairment in lipid and lipoprotein metabolism, with an increase in TG, LDL and LBP and a marked decrease of HDL." (PMID 18271959, 2008). "The present study purpose was to examine levels of HMGB1, LBP and PCT in patients with sepsis of different severity, in bacteraemic patients and in relation to the outcome of the patients." (PMID 17625012, 2007). "The aim of the present study was to investigate levels of HMGB1, LBP and PCT in a well-characterised sepsis cohort." (PMID 17625012, 2007). "Levels of HMGB1, LBP and PCT were higher in the severe sepsis group compared with the sepsis group (P < 0.01)." (PMID 17625012, 2007). "In a prospective cohort study, serum concentration of LBP was detected in patients with systemic inflammatory response syndrome (SIRS), sepsis, and septic shock to evaluate its ability to differentiate between infectious and non-infectious etiologies in SIRS and to predict prognosis." (PMID 41597433, 2026). "Plasma LBP levels of male and female SIRS/sepsis patients were similar." (PMID 39997462, 2025). "In contrast to Gram-negative infected SIRS/sepsis patients in our study, male mice exhibited elevated LBP levels when challenged with LPS in comparison to female animals." (PMID 39997462, 2025). "Our study found that sepsis patients, regardless of COVID-19 status, had similar plasma LBP levels in both sexes." (PMID 39997462, 2025). "Patients with sepsis and liver cirrhosis have lower LBP and CRP levels compared to sepsis patients without liver cirrhosis." (PMID 39997462, 2025). "Therefore, we also measured sepsis-related LPS (lipopolysaccharides, also called endotoxin) and LBP (LPS binding protein) levels." (PMID 38762592, 2024).
Sepsis (continued). "In our previous study of 102 critically ill severe sepsis and/or trauma patients with MODS, we aimed to assess the prognostic value and daily trend of IL-6, nCD64 expression, CRP and lipopolysaccharide-binding protein (LBP) in relation to the outcome measure of hospital mortality." (PMID 34945111, 2021). "Our data demonstrate that the selective removal of LBP may represent a therapeutic option to prevent PMT and the development of acute renal fibrosis in sepsis-induced AKI." (PMID 31357597, 2019). "The normal plasma level of LBP can be upregulated dramatically after inflammatory stimulation such as sepsis induced by gram-negative bacteria." (PMID 30165815, 2018). "Recently, some studies investigated candidate biomarkers to detect sepsis reported such as procalcitonin (PCT), C-reactive protein (CRP), lipopolysaccharide-binding protein (LBP), interleukins, provasopressin, and myeloid cells expressing triggering receptor-1 (TREM-1)." (PMID 28875483, 2017). "Recently, several studies have investigated the role of serum LBP in differentiating sepsis from non-infectious SIRS in different clinical settings." (PMID 27055115, 2016). "These properties made LBP a promising tool for the diagnosis of sepsis, and suitable to discriminate between non-septic systemic inflammatory response syndrome (SIRS) and sepsis." (PMID 27055115, 2016). "A further study in the same year investigated the levels of polymorphonuclear leukocyte surface BPI, plasma BPI, and plasma LBP in normal human volunteers who were administered Escherichia coli LPS and in patients with sepsis and Gram-negative infections." (PMID 26347737, 2015). "Thus, interfering with LBP/CD14 interactions has been considered for treating endotoxin-induced diseases, such as ARDS and sepsis." (PMID 25025695, 2014). "During the first 5 days of sepsis, median plasma concentrations of LBP and CRP were even higher in S than in NS and did not discriminate both groups as assessed by ROC analysis (AUC<.55; data not shown)." (PMID 21901123, 2011). "We studied the usefulness of serum procalcitonin (PCT), interleukin-6 (IL-6), lipopolysaccharide binding protein (LBP) levels and C-reactive protein (CRP) levels, in differentiating between systemic inflammatory response syndrome (SIRS) and sepsis in critically ill patients." (PMID 21687569, 2011). "To prospectively evaluate the performance of Lipopolysaccharide-Binding Protein (LBP) in prediction of hospital mortality and its correlation to C-reactive Protein (CRP), we studied sixty consecutive, postoperative patients with sepsis admitted to the university hospital intensive care unit." (PMID 21901123, 2011). "In the second week of sepsis, we found a marked re-increase of LBP and CRP in the nonsurviving group most likely as part of an inflammatory response to a recurrent or unresolved infection." (PMID 21901123, 2011). "Furthermore, LBP, IL-6 and CRP were significantly higher in children with severe sepsis compared to those ones with less severe sepsis (p < 0.001)." (PMID 20158885, 2010). "In a ROC analysis to distinguish between patients with noninfectious SIRS and patients with sepsis/severe sepsis, IL-6, LBP and CRP had an AUC of 0.87, 0.86 and 0.84, respectively; compared to 0.75 for PCT." (PMID 19578505, 2008). "In a ROC analysis to distinguish between patients with noninfectious SIRS and patients with sepsis/severe sepsis, IL-6, LBP and CRP had an AUC of 0.87 (95% CI 0.78–0.96), 0.86 (95% CI 0.77–0.95) and 0.84 (95% CI 0.75–0.92), respectively." (PMID 16569262, 2006). "Levels of LBP, IL-6 and CRP increased progressively with increasing severity of infection/sepsis." (PMID 16569262, 2006). "In conclusion, despite its involvement in the early immune response to bacterial infections, LBP has shown limited effectiveness in accurately discriminating sepsis from non-infectious inflammatory conditions, reducing its usefulness as an early diagnostic or rule-out biomarker." (PMID 41597433, 2026).